AHCY (adenosylhomocysteinase)
Description:
Catalyzes the hydrolysis of S-adenosyl-L-homocysteine to form adenosine and homocysteine. Binds copper ions (By similarity).
Synonyms: AdoHcyase; SAHH
Tractability: Small molecule: a structure with a bound ligand is known; a high-quality ligand is known; it has a high-quality binding pocket; it belongs to a druggable protein family. PROTAC: ubiquitination databases record sites on it; its protein half-life has been measured; a small molecule that binds it is known.
Target class: Enzyme; Hydrolase
Gene: Protein-coding gene on chromosome 20 (34,280,268 to 34,311,802, reverse strand). Ensembl gene ENSG00000101444.
Subcellular location: Cytoplasm; Melanosome; Nucleus; Endoplasmic reticulum
Subcellular location (Human Protein Atlas): Cytosol
Pathways (Reactome):
Metabolism: Metabolism of ingested SeMet, Sec, MeSec into H2Se; Methylation; Sulfur amino acid metabolism
Disease: Defective AHCY causes HMAHCHD
Gene Ontology:
Molecular function: adenosylhomocysteinase activity; protein binding
Biological process: S-adenosylmethionine cycle
Cellular component: cytosol; endoplasmic reticulum; extracellular exosome; nucleus; cytoplasm; melanosome
Genetic constraint (gnomAD): Loss-of-function variants: 24 observed, 46.41 expected, observed/expected ratio (o/e) 0.52, 90% interval 0.37 to 0.73. The upper end of that interval is the gene's LOEUF score, 0.73, which puts it in group 2 of 6, group 1 being the genes least tolerant of losing a copy. Missense variants: 449 observed, 621.65 expected, observed/expected ratio (o/e) 0.72, 90% interval 0.67 to 0.78. Synonymous variants: 245 observed, 242.95 expected, observed/expected ratio (o/e) 1.01, 90% interval 0.91 to 1.12.
Gene-disease validity (ClinGen):
ClinGen rates the evidence that AHCY causes each of these diseases.
hypermethioninemia with deficiency of S-adenosylhomocysteine hydrolase (autosomal recessive): Definitive.
Homologues: Orthologues: macaque AHCY (99% identical), chimpanzee AHCY (98% identical), mouse Ahcy (97% identical), mouse Ahcyl (97% identical), pig AHCY (97% identical), guinea pig AHCY (96% identical), zebrafish ahcy (86% identical), tropical clawed frog ahcy (86% identical), Drosophila melanogaster Ahcy (81% identical), Caenorhabditis elegans ahcy-1 (77% identical). Paralogues in human: AHCYL1 (51% identical), AHCYL2 (51% identical).
Diseases named in the same sentence as AHCY in open-access papers:
AHCY is named in the same sentence as 79 diseases in open-access papers, as found by Europe PMC text mining. Sharing a sentence is not in itself a finding about the gene and the disease. The quoted sentences say what the papers report.
breast carcinoma (13 papers, 2014 to 2024). "However, AHCY’s function as a tumor suppressor seems to be cell type specific, as AHCY inhibition is also linked to anti-migratory and anti-invasive activity in breast cancer cells and to enhanced apoptosis in high aggressive neuroblastoma." (PMID 33869213, 2021). "Among these prognosis-associated genes, four genes, AHCY, CBS, DNMT3A, and MTAP (p-value < 0.05), were common markers of poor prognosis for neuroblastoma and breast cancer." (PMID 36361596, 2022). "By the analysis of transcriptomic data of more than 1500 cancer cell lines and patient samples, we show that the high expression of four genes from the methionine metabolism pathway (AHCY, CBS, DNMT3A, and MTAP) is associated with poor prognosis for breast cancer and neuroblastoma patients." (PMID 36361596, 2022). "Four genes (AHCY, CBS, DNMT3A, and MTAP) from the methionine metabolism gene set are markers of poor prognosis for neuroblastoma and breast cancer patients." (PMID 36361596, 2022). "Among KEGG methionine metabolism genes, we have revealed five poor prognostic markers, including AHCY, CBS, DNMT3A, and MTAP, for neuroblastoma and breast cancer patients." (PMID 36361596, 2022).
hepatocellular carcinoma (9 papers, 2017 to 2025). A malignant tumor that arises from hepatocytes. "Mild inactivation of AHCY activity leads to the late onset of typical disease symptoms and the pathway for the development of hepatocellular carcinoma due to AHCY dysfunction." (PMID 36172354, 2022). "To elucidate AHCY-driven cancer-specific mechanisms, we pursued a multi-omics approach to investigate the effect of AHCY-knockdown on hepatocellular carcinoma cells." (PMID 30228286, 2018). "Key cancer-related pathways such as “Gastric cancer”, “Hepatocellular carcinoma” and “Proteoglycans in cancer” were prominently identified in network, bar and bubble plots, and genes such as NME1, PSAT1, AHCY and PIGR were significantly involved." (PMID 40567612, 2025). "AHCY knockdown leads to SAM depletion and proliferation rate reduction in hepatocellular carcinoma cells." (PMID 31828117, 2019).
colorectal cancer (7 papers, 2009 to 2025). A primary or metastatic malignant neoplasm that affects the colon or rectum. "For example, APC‐deficient colorectal cancer in a mouse model exhibited dysregulation of the methionine cycle due to the upregulated expression of adenosylhomocysteinase (AHCY), and pharmacological inhibition of AHCY effectively reduced intestinal tumor growth in APC‐deficient mice." (PMID 40552664, 2025). "S-Adenosylhomocysteine hydrolase (AHCY) can catalyze the hydrolysis of S-adenosylhomocysteine to adenosine and homocysteine in living organisms, and its abnormal expression is linked to the pathogenesis of many diseases including colorectal cancer (CRC)." (PMID 35927991, 2022). "S-adenosylhomocysteine hydrolase (AHCY) levels in colorectal cancer are disrupted, leading to an imbalance in methylation processes." (PMID 39839775, 2024). "TFF3, TFF1, SELE, AHCY, LCN2, CEACAM5, and RETN are consistently upregulated across a variety of datasets and analyzes, which supports their crucial roles in the underlying mechanisms of colorectal cancer progression." (PMID 39839775, 2024). "Seven proteins namely TFF3, LCN2, CEACAM5, TFF1, SELE, RETN, and AHCY proteins of both phases were found to be upregulated in colorectal cancer in human protein atlas database, also were significant in our UK Biobank dataset and had an essential function in CRC." (PMID 39839775, 2024). "Therefore, we first examined the AHCY expression in clinical samples of human colorectal cancer." (PMID 35927991, 2022). "Seven proteins, TFF3, LCN2, CEACAM5, TFF1, SELE, RETN, and AHCY were found to be upregulated in other databases and also in our UK Biobank where TFF3 and LCN2 were found to be the most significant proteins and were highly expressed in colorectal cancer." (PMID 39839775, 2024).
hypermethioninemia (7 papers, 2015 to 2024). "Pathogenic variants in the AHCY gene, which encodes the SAHH enzyme, causes hypermethioninemia, increased SAM and SAH with a significant imbalance in SAM/SAH ratio." (PMID 39512434, 2024). "S-adenosylhomocysteine hydrolase (AHCY) deficiency results mainly in hypermethioninemia, developmental delay, and is potentially fatal." (PMID 38003292, 2023).
neuroblastoma (7 papers, 2015 to 2023). Neuroblastoma (NB) is the most common solid, extracranial childhood tumor. "High expression of AHCY is associated with MYCN-amplified neuroblastoma and contributes to the enhanced proliferation of cancer cells." (PMID 36361596, 2022). "More recently, genetic variations of AHCY have been linked to different prognosis of children with neuroblastoma, thus providing evidence of the potential use of AHCY variants as a molecular biomarker." (PMID 33869213, 2021). "A previous study demonstrated that mutations in AHCY were associated with prognosis in neuroblastoma patients, suggesting that this gene could be considered as a potential prognostic factor in this context." (PMID 32020847, 2020). "Cocktails of small molecule inhibitors of CKS1B, AHCY, BLM, and PKMYT1 profoundly affected the growth of all neuroblastoma cell lines but selectively caused death of MYCN-amplified cells." (PMID 25477524, 2015). "Knockdown of AHCY in adrenergic high MYCN but not mesenchymal neuroblastoma cells impaired colony formation, which was associated with reduced GSH levels and reduction of GSH reduced-to-oxidized ratios." (PMID 35484422, 2022). "A recent study demonstrated that a signature consisting of five genes (AKR1C2, NCAN, AHCY, FBP2 and GALNT3) has potential prognostic values in neuroblastoma." (PMID 36701414, 2023). "CBS, AHCY and PHGDH expression was also elevated in mass spectrometry-based global proteomes from MYCN-amplified neuroblastoma tumors." (PMID 35484422, 2022). "In neuroblastoma, AHCY expression is elevated in MYCN-amplified tumor samples and neuroblastoma cell lines." (PMID 33869213, 2021). "The significance of BLM, AHCY, PKMYT1, and CKS1B in the pathogenesis of neuroblastoma is indicated by their elevated expression in MYCN-amplified tumor samples and in MYCN-overexpressing cells and their correlation with poor patient survival." (PMID 25477524, 2015). "Moreover, four genes from the methionine metabolism gene set, such, AHCY, CBS, DNMT3A, and MTAP, are markers of poor prognosis for neuroblastoma and breast, but not for colon and lung, cancer patients." (PMID 36361596, 2022).
viral infection (5 papers, 2014 to 2026). "AHCY function is further fine-tuned through a wide spectrum of posttranslational modifications and small-molecule interactions, linking it to transcriptional control, stress adaptation, and viral infection." (PMID 41638428, 2026).
bladder cancer (3 papers, 2020 to 2023). "In this study, we established the GMII consisting of eight glutamine metabolism-related genes (ENPP1, GALK1, TALDO1, CYP19A1, FASN, AHCY, SLC7A9, and HSPG2), a high value of which is associated with poor prognosis in bladder cancer patients." (PMID 36911676, 2023). "The expression of five of the eight GMII genes (TALDO1, AHCY, FASN, GALK1 and SLC7A9) in bladder cancer tissues was higher than that in normal tissues, while ENPP1, CYP19A1 and HSPG2 were down-regulated in tumor tissues (p < 0.05)." (PMID 36911676, 2023). "Results from overall survival analysis and disease free analysis with clinical data from TCGA revealed that core mRNAs in the coexpression networks, AHCY, C6orf136 and LRIG1, correlate with the progression and recurrence of bladder cancer significantly." (PMID 32065779, 2020).
colon carcinoma (3 papers, 2017 to 2023). "To solve this question, we studied the effects of knockdown or overexpression of AHCY on expression of Hh signaling-associated proteins in colon cancer cells, respectively." (PMID 35927991, 2022). "Collectively, AHCY knockdown inactivated the Hh signaling whereas AHCY overexpression enhanced the activation of Hh signaling in colon cancer cells." (PMID 35927991, 2022). "Several studies have demonstrated the connections between S-adenosylhomocysteine hydrolase (AHCY) and cancer; however, the roles of AHCY in colon cancer and WMP-induced anti-CAC effect remain to be determined." (PMID 35927991, 2022). "Our team has obtained a large number of unpublished data, and these data remind us that AHCY is a potential and promising target in colon cancer." (PMID 35927991, 2022). "AHCY overexpression enhanced, while its knockdown weakened the inflammation and oxidative stress in colon cancer cells." (PMID 35927991, 2022). "In order to shed new light on molecular aspects of AHCY deficiency, in particular any changes at transcriptome level, we enabled knockdown of AHCY expression in the colon cancer cell line SW480 to simulate the environment occurring in AHCY deficient individuals." (PMID 38003292, 2023). "Thus, in this study we investigated the effects of AHCY downregulation on the colon cancer derived model cell line SW480." (PMID 38003292, 2023). "Interestingly, AHCY was also linked to the regulation of inflammation and oxidative stress in colon cancer cells, and AHCY depletion led to the inhibition of inflammation and oxidative stress." (PMID 35927991, 2022). "Moreover, AHCY was found participating in the regulation of inflammation and oxidative stress in colon cancer cells." (PMID 35927991, 2022). "AHCY was high expression in clinical samples of colon cancer compared to the adjacent tissues." (PMID 35927991, 2022). "Moreover, AHCY was found to play essential roles in regulating tumor proliferation, colony formation, invasion, and tumor angiogenesis of colon cancer cells." (PMID 35927991, 2022). "Firstly, the expression of AHCY in nine colon cancer cell lines was examined by western blot." (PMID 35927991, 2022). "Compared to the adjacent noncancerous tissues, western blot showed that AHCY was highly expressed in clinical samples of human colon cancer." (PMID 35927991, 2022).
ischemic stroke (2 papers, 2020 to 2022). A stroke disorder caused by obstruction of blood flow to the brain, due to thrombotic (local blood clot formation) or embolic (due to a blood clot or other material traveling from another site) event. "This study aimed to determine the correlation between DNA methylation of the gene encoding S-adenosylhomocysteine hydrolase (AHCY) and the risk of ischemic stroke in 64 ischemic stroke patients and 138 patients with traumatic brain injury (control group)." (PMID 32020847, 2020). "In this case-control study, we explored the role of DNA methylation of AHCY as a risk factor for ischemic stroke in a Chinese population." (PMID 32020847, 2020). "As the homocysteine level is considered an independent predictor of severe neurological impairment in ischemic stroke patients, we hypothesized that DNA methylation of AHCY may play a key role in the pathological development of ischemic stroke." (PMID 32020847, 2020).
osteosarcoma (2 papers, 2023). A usually aggressive malignant bone-forming mesenchymal neoplasm, predominantly affecting adolescents and young adults. "Adenosylhomocysteinase is known to promote adenosine-induced apoptosis in HepG2 and esophageal cancer cells, also blocking the motility of the latter, and to inhibit autophagy in osteosarcoma cells in an MTORC1-independent manner." (PMID 37106816, 2023).
prostate carcinoma (2 papers, 2022 to 2025). A carcinoma that arises from epithelial cells of the prostate gland. "It demonstrates potent AHCY inhibition and antiviral activity, and although it has not advanced into clinical development, it has been investigated preclinically in prostate cancer with considerable efficacy." (PMID 40015640, 2025). "Besides, AHCY has been demonstrated as the molecular target of aristeromycin (a derivative of 3-deazaneplanocin A), and treatment of the prostate cancer cells with 3-deazaneplanocin A led to SAH accumulation." (PMID 35927991, 2022). "Interestingly, knockdown of AHCY by siRNA could also result in the accumulation of SAH and cell growth inhibition of prostate cancer, highlighting that AHCY participated in the regulation of tumor growth of prostate cancer." (PMID 35927991, 2022).
psoriasis (2 papers, 2023 to 2024). An autoimmune condition characterized by red, well-delineated plaques with silvery scales that are usually on the extensor surfaces and scalp. "Then, 5 potential hub genes (SOD2, PGD, PPIF, GYS1, AHCY) of psoriasis were identified by protein–protein interaction (PPI) networks using Metascape database." (PMID 36890558, 2023). "Together, the 5 hub genes (SOD2, PGD, PPIF, GYS1 and AHCY) play pivotal roles in the development of psoriasis." (PMID 36890558, 2023). "We found that SOD2, PGD, PPIF, GYS1 and AHCY are five hub genes in PPI networks, indicating the potential role in the psoriasis initiation and progression." (PMID 36890558, 2023). "Five potential hub genes of psoriasis were obtained, including SOD2, PGD, PPIF, GYS1 and AHCY." (PMID 36890558, 2023). "However, the potential role of PGD, PPIF, GYS1 and AHCY has not been explored in psoriasis." (PMID 36890558, 2023).
B-cell lymphomas (1 paper, 2020). "This study reveals one possible molecular mechanism how B-cell lymphomas can acquire resistance to DZNep, and proposes AHCY as a potential biomarker for investigation during the administration of EZH2-targeted therapy with DZNep." (PMID 32408898, 2020). "Although AHCY alterations are rare in primary B-cell lymphomas, it may still be important to screen for modifications of this gene in patients prior to the initiation of EZH2 based therapy with DZNep." (PMID 32408898, 2020).
cerebral infarction (1 paper, 2020). An ischemic condition of the brain, producing a persistent focal neurological deficit in the area of distribution of the cerebral arteries. "We compared the promoter methylation levels of two genes (AHCY and CBS) in peripheral blood DNA between the cerebral infarction case group and the control group." (PMID 33138824, 2020).
Cerebral ischemia (1 paper, 2023). Restriction of arterial blood supply to the brain associated with insufficient oxygenation to support the metabolic requirements of the tissue. "Thus, our findings suggest that chlorogenic acid has neuroprotective effects by controlling the level of adenosylhomocysteinase in cerebral ischemia." (PMID 37271817, 2023).
cerebrovascular disease (1 paper, 2020). "Therefore, AHCY methylation may regulate the enzymatic activity of AHCY, resulting in increased homocysteine levels in patients with cerebrovascular disease." (PMID 32020847, 2020).
Cirrhosis (1 paper, 2025). A chronic disorder of the liver in which liver tissue becomes scarred and is partially replaced by regenerative nodules and fibrotic tissue resulting in loss of liver function. "Serum EV-associated adenosylhomocysteinase (AHCY) expression was also positively correlated with the degree of cirrhosis, achieving over 90% rates of specificity, which exceeded the predictive power of Child–Pugh classification system." (PMID 40771315, 2025).
esophageal squamous cell carcinoma (1 paper, 2025). Esophageal squamous cell carcinoma (ESCC) is a type of esophageal carcinoma (EC) that can affect any part of the esophagus, but is usually located in the upper or middle third. "Moreover, our study delineates a novel pathway in esophageal squamous cell carcinoma whereby STIP1 enhances the interaction between AHCY and LDHA, enabling AHCY to recruit PRMT3 to methylate LDHA at R106." (PMID 41163796, 2025). "Our study elucidates a previously unrecognized oncogenic signaling axis in esophageal squamous cell carcinoma whereby the co‐chaperone STIP1 and metabolic enzyme AHCY are co‐opted to drive upregulation of the Warburg effect and promote ESCC progression." (PMID 41163796, 2025).
fetal hydrops (1 paper, 2023). "Deficiency of adenosylhomocysteinase leads to developmental brain disorders and fetal hydrops in humans." (PMID 37271817, 2023).
pneumonia (1 paper, 2019). An acute, acute and chronic, or chronic inflammation focally or diffusely affecting the lung parenchyma, caused by an infection in one or both of the lungs (by bacteria, viruses, fungi, or mycoplasma.). "Moreover, the expression of eight DEPs (PECAM1, PGLYRP1, AHCY, BHMT, EML3, ICOSLG, IGHV3‐23 and RTN4RL2) in normal and pneumonia groups (two patients) was quite different from that in the KD group." (PMID 30761252, 2019). "Moreover, the expression of eight of these 30 DEPs (PECAM1, PGLYRP1, AHCY, BHMT, EML3, ICOSLG, IGHV3‐23 and RTN4RL2) clustered normal and pneumonia samples into one group and clustered KD samples into another group, which heightens the importance of these eight DEPs in KD." (PMID 30761252, 2019).
tubulointerstitial nephritis (1 paper, 2021). "Dolichyl-diphosphooligosaccharide-protein glycosyltransferase 48kDa subunit, adenosylhomocysteinase, tubulointerstitial nephritis antigen, calponin domain containing protein, 3 ketoacyl coenzyme A thiolase, elongation factor 1-alpha and serpin domain containing protein appeared as typical of EE." (PMID 33760829, 2021).